RHOA (ras homolog family member A)
Diseases named in the same sentence as RHOA in open-access papers (continued):
Sharing a sentence is not in itself a finding about the gene and the disease.
infection (continued). "After infection with RhoA T19N or RhoA Q63L adenovirus for 48 hr, Wnt5a CM did not up-regulate the expression of phospho-MLC, which is consistent with the effect on cytoskeleton rearrangement." (PMID 23844260, 2013). "Our data now clearly demonstrates using an intranasal mouse model of infection that F11-mediated inhibition of RhoA signalling enhances the spread of vaccinia infection not only in cell monolayers but also in vivo." (PMID 20041165, 2009). "However, infection with L. infantum, but not with L. amazonensis or L. braziliensis, led to increased Rac1, Cdc42, and RhoA expression compared to uninfected controls in a 3D environment." (PMID 37576604, 2023). "To determine whether the formation of RhoA-mediated actin cage could interfere with DMV escape, we investigated the percentage of S. flexneri DMVs that were surrounded by F-actin during infection of mbYFP-expressing HT-29 cells infected with CFP-expressing bacteria." (PMID 35202448, 2022). "Furthermore, we discovered that the presence of RhoA downregulates ARF1 activation, while ARF1-GTP inhibits RhoA activation, highlighting cross talk between two small GTPases to coordinate PTM-MT and actin scaffolds during infection." (PMID 34903051, 2021). "Here, we demonstrate that early infection with PSaV in polarized LLC-PK cells in either the presence or absence of bile acids activates the RhoA/ROCK/MLC signaling pathway, whose inhibitors reverse the early PSaV infection-induced dissociation of TJs and reduce PSaV replication." (PMID 33692204, 2021). "As shown, the ARHGAP5 exhibited a significantly decreased expression in hBMECs along with the infection, while in contrast, the RhoA exhibited an increasing expression in response to the infection, which is exactly consistent with the concept that ARHGAP5 could negatively regulate RhoA." (PMID 31766605, 2019). "This was suggested from a GTPase pulldown assay showing that active RhoA and Cdc42 were no longer detected in ZJO-infected cell lysates after 1 h of infection, even if they were stimulated with the nonhydrolyzable GTP analogue GTPγS." (PMID 29252102, 2018). "Infection with the F11-VK virus, however, did not result in a reduction in the level of GTP-bound RhoA at 8 hours post infection as seen with WR." (PMID 20041165, 2009). "In contrast, treatment with the synthetic AIM2 inflammasome ligand poly(dA:dT) did not inhibit RhoA-GTP activity in any of the genotypes tested, suggesting that infection has a distinct ability to integrate the AIM2-mediated signaling and RhoA signaling cascades to influence Pyrin activation." (PMID 34471287, 2021).
cardiovascular diseases (30 papers, 2012 to 2025). "Potassium chloride can cause calcium sensitization via the activation of the RhoA-Rho kinase pathway, which is involved in many cellular functions and the pathogenesis of cardiovascular diseases and DM." (PMID 40141797, 2025). "Rho-associated kinase (ROCK), an immediate downstream target protein of RhoA, has been revealed to be associated with endothelial dysfunction and cardiovascular diseases." (PMID 25280018, 2014). "The RhoA/ROCK signal mediates the process of cardiovascular diseases by regulating biological processes such as inflammation, differentiation and apoptosis." (PMID 37278388, 2023). "RhoA and ROCK have been reported to be involved in the pathogenesis of the cardiovascular disease, while 8 weeks of exercise reduces RhoA and ROCK gene expression." (PMID 36036015, 2022). "Our findings suggest that the RhoA/ROCK signaling pathway is important in the pathogenesis of CAD, so the inhibition of the activity of RhoA/ROCK-1 pathway would be beneficial in treating cardiovascular diseases." (PMID 34236817, 2022). "The RhoA/ROCK-1 pathway plays an important role in various cellular events involved in the pathogenesis of cardiovascular diseases as well as in the development of the effects of many vasoactive substances." (PMID 34236817, 2022). "Another reason is the considerable influence of RhoA/ROCK pathway over various vasoactive substances involved in the pathogenesis of cardiovascular diseases, such as angiotensin II, 5-hydroxytryptamine, thrombin, and platelet-derived growth factor." (PMID 34236817, 2022). "Inhibition of the activity of RhoA/ROCK-1 pathway would be beneficial in treating cardiovascular diseases since this pathway plays an important role in the development of these diseases." (PMID 34236817, 2022). "The first reason for this interest is that the RhoA/ROCK signaling pathway plays an important role in various cellular functions involved in the pathogenesis of cardiovascular diseases." (PMID 34236817, 2022). "In recent years, the RhoA/ROCK-1 signaling pathway aroused interest among researchers of cardiovascular diseases." (PMID 34236817, 2022). "Although the RhoA signaling pathway has been widely studied in cardiovascular diseases, it is rarely investigated with respect to CNS diseases, especially VaD." (PMID 30505270, 2018). "Studies demonstrated that RhoA/ROCK activation played an important role in various cardiovascular diseases, and acted as a convergent node in the pathogenesis of vascular diseases." (PMID 29641598, 2018). "Both the urotensinergic system and the RhoA-ROCK pathway play crucial roles in cardiovascular diseases." (PMID 28684968, 2017). "RhoA, a small GTPase protein, has been shown to play an essential role in a variety of cardiovascular diseases." (PMID 23118936, 2012). "In addition, RhoA gene expression levels increase in patients with cardiovascular disease while decreasing with exercise (70% of VO2max)." (PMID 36036015, 2022). "Thus, the RhoA/ROCK pathway has become a target for the development of drugs for treating cardiovascular diseases." (PMID 35242876, 2022). "RhoA activation has significant effects on various cardiovascular diseases, mainly HTN." (PMID 34233719, 2021). "Upregulation of the RhoA/ROCK pathway is common in many cardiovascular diseases." (PMID 32724667, 2020). "Importantly, RhoA GTPases are master orchestrators of platelet physiology by inducing the vascular effects of various vasoactive factors to promote hemostasis, and play a major role in the development of cardiovascular disease." (PMID 38087280, 2023). "Many studies have proven the involvement of the RhoA/ROCK pathway in autoimmune and cardiovascular diseases and the beneficial effects of its downregulation." (PMID 38540212, 2024). "The RhoA/ROCK signaling pathway is shown to have important functions on vascular physiology and cardiovascular disorders." (PMID 34236817, 2022).
cardiovascular diseases (continued). "The RhoA-ROCK pathway plays an important role and is a novel therapeutic target for cardiovascular diseases." (PMID 28684968, 2017). "Statins, primarily used for primary and secondary prevention of cardiovascular diseases worldwide, could inhibit YAP through inhibiting RhoA activity." (PMID 29449645, 2018). "The data showed increased expression of ROCK1 (but not RhoA) in all our experimental groups compared to control VECs, and appear to support previous finding regarding ROCK1 signaling involvement in the pathogenesis of various cardiovascular diseases." (PMID 38474293, 2024). "Cardiac RhoA expression was significantly decreased in patients with idiopathic DCM compared with control subjects (average age: 38.5 ± 10.8 years; male/female (n): 12/3) who died accidentally without cardiovascular diseases." (PMID 36758801, 2023).
neurodegenerative disease (19 papers, 2011 to 2025). A disorder of the central nervous system characterized by gradual and progressive loss of neural tissue and neurologic function. "Based on these results, some caution should be taken regarding the use of RhoA inhibitors as a therapeutic approach to ameliorating inflammation and neuron loss in neurodegenerative diseases." (PMID 32825197, 2020). "Moreover, in models of neurodegenerative diseases, RhoA inhibition has been associated with reduced M1 activation, facilitating inflammation resolution, and limiting tissue damage." (PMID 40821819, 2025). "Aberrant RhoA signaling has been identified in neurodegenerative diseases such as AD, which shares its etiology with PE53,54." (PMID 38760513, 2024). "In this review, we summarize the current knowledge of RhoA regulation and downstream cellular functions with an emphasis on the role of RhoA signaling in neurodegenerative diseases and the therapeutic potential of RhoA inhibition in neurodegeneration." (PMID 35563826, 2022). "This is followed by a summary of downstream targets of RhoA relevant to cellular functions involved in neurodegenerative diseases." (PMID 35563826, 2022). "In this article, we review current knowledge on the specific role of RhoA signaling in neurodegenerative diseases and the potential of interfering with this signaling pathway for disease intervention." (PMID 35563826, 2022). "Additionally, strategies to inhibit RHOA signaling improve axonal regeneration of injured motor axons and delay onset and extend survival in neurodegenerative disease models of ALS." (PMID 36901711, 2023). "Therefore, broad inhibition of RhoA signaling is widely believed to be a viable approach to curtail neurodegenerative diseases as we will discuss in more detail." (PMID 34054432, 2021). "However, inhibition of RhoA using C3 inhibited Cx43 upregulation by mitochondrial complex inhibitors, suggesting that RhoA activity affects Cx43 expression and hemichannel function in neurodegenerative diseases." (PMID 32070020, 2020). "Although recent studies have shown the dysregulation of RhoA in a variety of neurodegenerative diseases, the role of RhoA in prion pathogenesis remains unclear." (PMID 28300846, 2017). "Although it was found that CNF1 treatment led to prolonged activation of Rac1 in comparison to that of RhoA in mice and rats, similar results obtained point to the potential complexity of how activation or inactivation of Rho GTPases may positively modify neurodegenerative diseases." (PMID 34054432, 2021). "Interestingly, also in these neurodegenerative diseases activation of RhoA has been implied, suggesting that the RhoA-induced suppression of the HSR may represent a more general feature of diseases related to proteotoxicity." (PMID 26193369, 2015). "Further studies are needed to confirm whether the RhoA/ROCK pathway is induced by METH abuse in animal models and, by extension, with METH-developed neurodegenerative diseases." (PMID 40149876, 2025). "RhoA mediated suppression of the HSR sensitizes cells for proteotoxic stress and might therefore be of relevance in various age-related diseases, including cardiac and neurodegenerative diseases." (PMID 26193369, 2015).
inflammation (13 papers, 2014 to 2023). Aberrant reaction of the microcirculation characterized by movement of fluid and leukocytes from the blood into extravascular tissues. "On the contrary, our present work shows that deletion of RhoA specifically in AT2 cells causes an increase in allergen-induced Th2-associated airway inflammation." (PMID 34101619, 2021). "Together, our data demonstrate a unique role for RhoA in AT2 cells in regulating allergen-induced Th2-associated airway inflammation." (PMID 34101619, 2021). "Strikingly, some of these proteins, such as RhoA or guanylate-binding protein-1 (GBP-1) have been associated with gut inflammation and IBD." (PMID 29051760, 2017). "In vascular smooth muscle cells, induced by vasoconstrictor angiotensin II, RHOA mediates phospho-Ser536 nuclear factor κB/RelA subunit exchange on the IL-6 promoter, thereby mediates IL-6 expression and vascular inflammation." (PMID 37781036, 2023). "Our study showed that although total RhoA and p120-bound RhoA were unchanged, RhoA activity is strongly increased in airway inflammation." (PMID 24995336, 2014). "In addition, mice with a genetic deletion of RhoA in intestinal epithelial cells (IECs) exhibited spontaneous chronic intestinal inflammation, and RhoA signaling was found to be downregulated in CD patients." (PMID 36690621, 2023). "Furthermore, disruption of RhoA in T cells inhibits T‐cell activation and Th2 differentiation and protects against allergen‐induced airway inflammation through affecting several metabolic pathways, such as glycolysis and oxidative phosphorylation." (PMID 32355562, 2020). "To study whether p120 activation of NF-κB in airway inflammation is through RhoA, we investigated RhoA and its activity in 16HBE 14o-cells." (PMID 24995336, 2014). "Further research found that deletion of myeloid Notch1 activity triggers RhoA/ROCK signaling and aggravates liver inflammation." (PMID 37370115, 2023). "p120 directly co-precipitates with RhoA, and its down-regulation activates RhoA, which then leads to IκBα degradation and NF-κB-p65 translocation, implying that p120 has an effect on NF-κB signaling in CSE-exposure induced airway inflammation." (PMID 27586697, 2016).
renal disease (10 papers, 2015 to 2024). "And insufficient RhoA/mDia/stress fibers/YAP pathway activity in podocyte may be one common reason that causes proteinuria in many kidney diseases." (PMID 27389190, 2016). "Thus, the aim of this study is to test whether RhoA deficiency could induce podocyte apoptosis and explore its mechanism, which may be one common reason that causes proteinuria in many kidney diseases." (PMID 27389190, 2016). "Ras homolog gene family, member A (RhoA), is an important protein involved in the development of various kidney diseases and it is also an important upstream activator of YAP." (PMID 33818281, 2021). "A previous study indicated that RhoA stabilizes the foot process structure of podocytes, thereby preventing proteinuria and related renal disease; however, inhibition of RhoA increases the motility of podocytes and results in proteinuria." (PMID 33818281, 2021). "Previously, it was described that RHOA knockdown (the effect observed in HEK MIR185 KOhom cell line) in podocytes led to increased apoptosis, a process commonly associated with the development of kidney diseases." (PMID 38413914, 2024). "Although RhoA, Rac, and Cdc42 are required for normal cellular functions, Rac1 overexpression or activation may be involved in the development of renal diseases, including DN." (PMID 30770784, 2019). "Maintaining necessary RhoA would be one potent way to prevent proteinuria kidney diseases." (PMID 27389190, 2016). "It has been reported that podocyte-specific knockout of RhoA does not cause renal disease in mice." (PMID 36096674, 2022).
cardiac disease (9 papers, 2015 to 2025). "Further research is thus needed to unravel the complex regulation and effects of RhoA activation in immune cells and the impact on immune responses linked to cardiac diseases." (PMID 34359851, 2021). "This review summarizes recent advances in understanding the role of RhoA in the heart and its signaling pathways to prevent progression of heart disease." (PMID 39122698, 2024). "In this review we provide an update on the role of RhoA at the juncture of immune cell activation, inflammation and cardiac disease." (PMID 34359851, 2021). "Present review aims at summarizing the possible role RhoA plays in cardiac disease via mediating the host immune system and how it can be exploited therapeutically to improve cardiac health of patients." (PMID 34359851, 2021). "RhoA has been shown to be beneficial in cardiac disease models when overexpressed in cardiomyocytes, whereas its role in cardiac fibroblasts is still poorly understood." (PMID 26448568, 2015). "In addition, statins are known to be effective inhibitors of RhoA-dependent signaling, and further research could lead to new therapeutic approaches for cardiac diseases in this context." (PMID 34359851, 2021). "The previous studies have also identified additional miR-185 target genes, such as RhoA, Cdc42, and Stim1, that are pro-hypertrophic in the heart, suggesting further that miR-185 is a strong anti-hypertrophic miRNA in vivo and a potent therapeutic target for cardiac diseases." (PMID 25767890, 2015). "Through KEGG enrichment analysis, the CALM/MLCK/p‐MLC2 and RHOA/ROCK/p‐MLC2 signalling pathways were a higher number of enriched genes, which were important signalling pathways involved in the process of cardiac disease." (PMID 41235503, 2025). "Since the enhanced production of reactive oxygen species is a putative stimulation process of the RhoA system for PM2.5, males might be more prone to heart disease when exposed to PM2.5." (PMID 36977056, 2023). "Additionally, there are reports indicating that the inhibition of MMP-2 and 9 activation may occur through the inhibition of the RhoA/ROCK pathway, but this issue has not yet been widely studied in heart diseases, although metalloproteinases play an important role in their pathomechanism." (PMID 38540212, 2024).
adenocarcinoma (8 papers, 2014 to 2024). A common cancer characterized by the presence of malignant glandular cells. "Gain-of-function mutations of RhoA occur specifically in poorly differentiated adenocarcinomas." (PMID 29951557, 2018). "The changes in median IHC scores with decitabine were 30 (adenocarcinomas) versus 20 (others) for RhoA (P = 0.63), 30 (adenocarcinomas) versus 12 (others) for RFC1, -5 (adenocarcinomas) versus 0 (others) for FOLR1 (P = 0.89) and 0 (adenocarcinomas) versus 0 (others) for GLUT4 (P = 0.96)." (PMID 24401732, 2014). "In vitro experiments using the adenocarcinoma cell lines A549 and H1299 and the squamous cell line, SK-MES-1 demonstrated that KLHL38 promotes migration and invasion by upregulating RhoA and MMP9 and downregulating E-cadherin." (PMID 34050138, 2021). "RHOA mutations recurrently occur in non-SRCC diffuse-type GC (i.e., poorly differentiated adenocarcinoma)." (PMID 35322078, 2022). "DGKζ protein levels, Rac1 and RhoA activity, and PAK phosphorylation were measured in the non-metastatic SW480 adenocarcinoma cell line and its highly metastatic variant, the SW620 line." (PMID 24646293, 2014).
bacterial infection (7 papers, 2018 to 2025). "We investigated the effects of ursolic acid (UA), a traditional Chinese medicine with anti-fibrotic effects, on intestinal damage and bacterial disorder through the RhoA pathway." (PMID 31736766, 2019). "Taken together, our results identified a new hFcLec4-β-integrin-RhoA-mediated phagocytic pathway against bacterial infection." (PMID 30233567, 2018). "Our study identified a new hFcLec4-β-integrin-RhoA mediated phagocytic pathway against bacterial infection in shrimp innate immunity." (PMID 30233567, 2018). "In summary, our study found that RhoA participates in hFcLec4-β-integrin-mediated phagocytosis, which protects the host against bacterial infection." (PMID 30233567, 2018). "In addition, host cells specifically recognize inactivation of RhoA by Yersinia effectors YopE and YopT and then activate pyrin inflammasome and pyroptosis to restrict bacterial infection." (PMID 32657447, 2020). "The results indicated that RhoA might inhibit bacterial infection by enhancing phagocytosis in shrimp." (PMID 30233567, 2018). "Therefore, our study identified a new hFcLec4-integrin-RhoA dependent phagocytosis against bacterial infection in shrimp." (PMID 30233567, 2018). "In addition, vitamin D may protect the vagina from bacterial infection by increasing the stability, proliferation and differentiation of stratified squamous epithelial cells through activation of the VDR, p-RhoA and p-Ezrin pathways, as suggested in other systems." (PMID 40469676, 2025).